NGF (nerve growth factor)
Diseases named in the same sentence as NGF in open-access papers (continued):
Sharing a sentence is not in itself a finding about the gene and the disease.
Stroke (continued). "In particular, the phosphorylation of CREB following activation of the PI3K/Akt pathway induces post-stroke restoration through the upregulation of neurogenic agents, such as nerve growth factor and brain-derived neurotrophic factor." (PMID 35405992, 2022). "DAPs can also significantly upregulate the expression of glial cell derived neurotrophic factor (GDNF) and nerve growth factor NGF, suggesting the neuroprotective effect of DAPs after stroke." (PMID 36235835, 2022). "Of these four neurotrophins, only two, BDNF and NGF, are well studied as potential stroke treatments." (PMID 35283994, 2022). "This review will outline the current state of preclinical and clinical research surrounding the potential for BDNF and NGF to become treatment options for patients following stroke." (PMID 35283994, 2022). "The neurotrophic factors transcripts including BDNF, GDNF, NGF, and NT‐3 were measured 7‐day post‐stroke." (PMID 35715988, 2022). "In the case of NGF, the obtained results indicated that the stroke itself triggers the endogenous protective mechanism related to the action of this factor." (PMID 34360581, 2021). "Specifically, the intense exercise protocol showed a significant increase in the mRNA expressions of HIF-1α, TrkB, CREB, BDNF, and NGF at different time points as compared to the stroke groups." (PMID 33625674, 2021). "Activated reactive astrocytes protect neurons after stroke by producing a variety of neurotrophic factors, including nerve growth factor, basic fibroblast growth factor, BDNF, and glial cell–derived neurotrophic factor." (PMID 34234667, 2021). "The increase in the level of NGF mRNA in the frontal cortex and dorsal striatum and upregulation of the NGF protein in the dorsal striatum with no change in the level of TrkA suggests an intensification of the NGF-TrkA protective signaling pathway by stroke." (PMID 34360581, 2021). "We evaluated local striatal cholinergic neuron survival and size, as well as neuropil changes, as measures of NGF-responsiveness at one week after hydrogel injections into stroke lesions." (PMID 33277474, 2020). "To determine hydrogel FBR effects on molecular delivery to CNS injuries we injected hydrogels loaded with NGF into mouse CP at 48 h after initiating a large focal stroke lesion via a 2 μL injection of L-NIO." (PMID 33277474, 2020). "The ability of thissystemically active NGF mimetic to protect pancreatic β-cells is ofpractical importance, because this compound is currently being investigated asa treatment for strokes, and the “coexistence” of stroke anddiabetes is well established." (PMID 31024748, 2019). "There is a correlation between the severity of neurological impairment in patients that have suffered a cerebrovascular accident and the nerve growth factor (NGF) level." (PMID 29720604, 2018). "For example, brief daily treadmill running for 3 weeks prior to stroke reduced infarct volumes in the frontoparietal cortex and dorsolateral striatum, and these effects were correlated with upregulation of NGF and BDNF in cortical neurons and striatal glia." (PMID 24818146, 2014). "In addition, NYT, in combination with physical exercise, improved sensorimotor function by stimulating BDNF/ TrkB and NGF/ TrkA, and by activating the Akt pathway in stroke models." (PMID 40361157, 2025). "It demonstrates that NGF is involved in multiple processes in neurogenesis after stroke." (PMID 36741282, 2023). "Promoting NGF secretion through exercise activates the synapses and thereby improves memory and judgment and increases the recovery rate of damaged brains, such as those of AD and stroke patients." (PMID 38003937, 2023). "Meanwhile, activities could induce the emission of neurotrophic factors, involving brain-derived neurotrophic factor (BDNF) and nerve growth factor (NGF), which could promote motor, cognitive and sensory retention in post-stroke patients." (PMID 36307774, 2022).
Stroke (continued). "Determining the role of BDNF and NGF in stroke and TBI is complex and often contradictory." (PMID 35283994, 2022). "NGF improved neuron differentiation and survival in a rat model of stroke." (PMID 35928573, 2022). "However, by activating late effector genes involved in post-stroke regeneration (NGF, bFGF, etc.), c-Fos is involved in the prevention of neuronal death in ischemic conditions." (PMID 34201112, 2021). "Given that BASP1 is similarly upregulated after stroke, its increase may also be mediated by NGF and BDNF." (PMID 33015061, 2020). "Despite the important role of the nerve growth factor in the survival and maintenance of neurons in ischemic stroke, data regarding the relationships between variations in the encoding gene and stroke are lacking." (PMID 29499660, 2018). "Genomic loci that are associated with increased stroke susceptibility and were reported by recent GWAS in European, non-Hispanic black and Hispanic ancestry samples do not include NGF and NGFR genes." (PMID 29499660, 2018). "Therefore, it is still in great need to further investigate the mechanism of BBB in hypoxic-ischemic state and enhance the permeability of exogenous NGF, thus improving the prognosis of patients with hypoxic and ischemic encephalopathy as strokes." (PMID 27843750, 2016). "MMP-2 is up-regulated in EC exposed to inflammatory cytokines such as interleukin-1-beta and growth factors including nerve growth factor, where in vivo, it promotes capillary invasion and so is probably increased in active stroke regions undergoing remodelling." (PMID 19292924, 2009). "Therefore task state fNIRS combined with the expression of BDNF and NGF factors in peripheral blood can be considered as a promising biomarker of cognitive deficits after stroke, which can predict the therapeutic response for the modulation of functional brain networks in PSCI." (PMID 40948655, 2025). "Intranasal delivery of NGF via the olfactory bulb and the trigeminal nerve pathways, leads to substantial concentrations of this neurotrophin into the brain, mainly in the frontal and parietal cortices, thalamus, cerebellum and striatal level, which are most often affected by stroke and TBI." (PMID 37789391, 2023). "High serum NGF concentrations are associated with good functional outcome following acute ischemic stroke in humans, indicating that BBB-permeable NGF conjugates could be useful therapeutic agents for stroke patients." (PMID 34572573, 2021). "L-NIO stroke injury triggered a significant loss of ChAT-positive neurons in the ipsilateral striatum; and NGF delivered from DCHMO, but not from DCHK or DCHMM, rescued the number of ChAT-positive neurons such that they were comparable to uninjured contralateral striatum." (PMID 33277474, 2020). "Also, the combination therapy of mesenchymal stem cells and NGF in stroke patients might also be promising to improve the life quality of patients." (PMID 27843750, 2016). "Ten proteins (including BCAN, NCAN, beta-NGF, SIGLEC1 and VWC2) were common to both the acute and convalescent stroke phase, but there were also differing examples." (PMID 40316737, 2025). "It was proved, in studies involving rodent models of stroke and traumatic brain injury (TBI), that the activation of nerve growth factor (NGF) and brain-derived neurotrophic factor (BDNF) signaling promotes neuroprotection, synaptogenesis, and neurogenesis." (PMID 38397420, 2024). "Moreover, in the hippocampus of the ischemic groups, as well as in the AP39 pretreated groups, the downregulation of caspase 3 activation may arise from the enhanced signaling of NGF-TrkA, and this is consistent with other data indicating the protective effects of NGF during a stroke." (PMID 34360581, 2021). "Notch pathway was involved in AST induced differentiation of NSCs, NGF, IL-7, and BDNF-TrkB pathway took part in proliferation and the neuronal differentiation of NSCs after stroke in vivo." (PMID 33716673, 2021).
Stroke (continued). "We identified colocalization signals at several established single trait loci such as TCF21, ADAMTS7, and LIPA for CAD, and NGF, FHL5, TSPAN2, and SLC24A3 for stroke." (PMID 31917787, 2020). "Such beneficial upregulation of NGF and BDNF was accompanied by an increase in GAP-43 levels when optogenetic stimulations were provided after stroke." (PMID 33015061, 2020). "In rodent models of stroke and TBI, the activation of NGF and BDNF signaling was shown to promote neuroprotection, synaptogenesis, and neurogenesis." (PMID 33015061, 2020). "This longer oxygen cycling (treated stroke by HBO for repetitive schedules for 3 weeks) therapy orchestrated gliosis and trophic factor production (BDNF, NGF, and GDNF) and decreased harmful effects by neutrophils in the early phase." (PMID 23533308, 2013). "For example, in a rodent stroke model, a PEG-based hydrogel loaded with neurotrophic factors like BDNF or NGF was injected into the lesion cavity; it gradually released these proteins over several weeks, enhancing neuronal survival and axon extension compared to the untreated lesions." (PMID 40981369, 2025). "Our results showed that the BDNF, NGF, 5-HT, and 5-HIAA levels were upregulated after the rTMS treatment, which likely contributed to improvements in cognitive function and quality of life in the patients with stroke." (PMID 40109842, 2025). "A total of 288 stroke patients from three hospitals will be recruited and randomly allocated to four groups: acupuncture + placebo, acupuncture + NGF, SMES + placebo, and SMES + NGF, in a 1:1:1:1 ratio." (PMID 39033586, 2024). "For subtypes of stroke, IS and ICH, higher levels of growth regulated oncogene-α, beta nerve growth factor, IL-18, macrophage colony-stimulating factor, and induced protein 10 upregulated the risk factors while lower levels of IL-2ra and IL-17 upregulated the risk factors." (PMID 38089678, 2023). "From these studies, it is clear that neurotrophins, specifically BDNF and NGF, administered directly and indirectly have a growing role in increasing neurogenesis and functional recovery after stroke and TBI and that BDNF and NGF have a synergistic role in motor learning and cognitive recovery." (PMID 35283994, 2022). "For instance, the systemic administration of RVG-EVs loaded with nerve growth factor (NGF) protein along with NGF mRNA significantly increases the expression of NGF in the infarcted cortex, reduces inflammation, and promotes cell survival in stroke." (PMID 36559145, 2022). "Indeed, genetic manipulation of neurotrophic factor expression, such as nerve growth factor (NGF) or glial-derived neurotrophic factor (GDNF) overexpression, have shown success in experimental models of clinical diseases including stroke." (PMID 33323541, 2020). "The fourth group of potential stroke biomarkers is represented by the brain-derived neurotrophic factor (BDNF), glial cell line–derived neurotrophic factor (GDNF), and nerve growth factor (NGF)." (PMID 31701356, 2020). "NGF delivered from DCHMO but not DCHK or DCHMM stimulated an increase in the mean ChAT intensity in the ipsilateral neuropil compared to the untreated stroke." (PMID 33277474, 2020). "In addition, NGF and PDGF mediate sildenafil neuroprotective effects in stroke and anti-proliferative effect on human pulmonary artery smooth muscle cells." (PMID 27438594, 2016). "Engraftment of CPs in adult stroke models reduced infarct size and improved neurological function, in part via secretion of glial cell line-derived neurotrophic factor (GDNF), brain-derived neurotrophic factor (BDNF), and nerve growth factor (NGF)." (PMID 25426016, 2014). "In addition, EA may promote synaptic plasticity after stroke by protecting and improving synaptic ultrastructure in the rat ischemic cerebral cortex and increasing the expression of synaptophysin P38, GAP-43, NGF and BDNF." (PMID 36741282, 2023).
Stroke (continued). "Neurotrophic factors from NGF (nerve growth factor), GDNF (glial cell-derived neurotrophic factor), and BDNF (brain-derived neurotrophic factor) may attenuate the neurotoxic inflammatory response after a stroke." (PMID 33042113, 2020). "In addition, increased NGF and BDNF expressions may contribute to the neuroinflammation-induced neuroprotection observed in acute brain injuries and early stages of stroke." (PMID 23651534, 2013). "In addition, various neurotrophic factors secreted by astrocytes, such as nerve growth factor (NGF), brain-derived growth factor (BDNF), erythropoietin (EPO), vascular endothelial growth factor (VEGF), and glial derived neurotrophic factor (GDNF), are increased after stroke." (PMID 36159395, 2022). "Indeed, brain delivery of exogenous neurotrophic factors, such as the neurotrophin nerve growth factor (NGF) and brain-derived neurotrophic factor (BDNF), can reduce infarct volumes by 60–90% with near total restoration of behavioral function in experimental stroke models." (PMID 24818146, 2014). "Incorporating nerve growth factor (NGF) into a comprehensive strategy may prove beneficial, particularly in non-neurodegenerative conditions such as stroke, trauma, and neuropathies." (PMID 40153582, 2024). "In vitro and in vivo analyses of NSC-derived NGF demonstrated that the NSC-derived, neurotrophin-modulated MHC expression correlated with the degree of transient symptomatic relief in stroke rats and promoted no secondary injury, such as apoptotic cell death and inflammation." (PMID 20727165, 2010).
Cognitive impairment (71 papers, 2011 to 2025). Abnormal cognition is characterized by deficits in thinking, reasoning, or remembering. "Taurine increases protein expression of BDNF and NGF, Significantly improved cognitive impairment caused by HBCDs in developing rats." (PMID 36187803, 2022). "The shift inthe proNGF/NGF ratio towards the precursor is considered to be the main reasonbehind the cholinergic deficit that causes cognitive impairment." (PMID 28740732, 2017). "Furthermore, one study demonstrated that the chronic injection of α2AP into the medial prefrontal cortex inhibits the NGF maturation induced by plasmin, causing cholinergic degeneration and cognitive impairment." (PMID 33059734, 2020). "In contrast to NGF, an increase in pro-NGF is linked to AD and to mild cognitive impairment." (PMID 31191244, 2019). "Neuronal synaptic growth requires NGF, which is a neurotrophic factor that plays a critical role in the differentiation, protection, and maintenance of cholinergic neurons, among which cholinergic neuronal dysfunction is associated with cognitive deficits." (PMID 28415680, 2017). "Thus, the NGF signaling pathway may provide insight into the mechanisms underlying chemotherapy-induced cognitive impairment." (PMID 35216124, 2022). "SGL has demonstrated improvements in cognitive impairment by reducing microgliosis and astrogliosis, and by increasing nerve growth factor (NGF) levels in Aβ- and scopolamine-induced animal models of dementia." (PMID 41155570, 2025). "Altered levels of neurotrophins such as NGF, BDNF, NT3, and NT4, as well as growth factors like IGF1, VEGF, and FGF, have been associated with cognitive deficits, sensory processing abnormalities, and behavioral issues in ASD patients." (PMID 40004071, 2025). "Another clinical trial (NCT04041349) randomized 510 patients with cognitive impairment due to cerebral small-vessel disease into two groups: the standard treatment group and the NGF-treated group." (PMID 39639374, 2024). "NGF protects neurons from ethanol-induced cytotoxic damage and affects recovery from cognitive deficits after brain damage." (PMID 38928583, 2024). "NGF offers neuroprotection against ethanol-induced cytotoxic damage and aids in the recovery from cognitive deficits post-brain injury." (PMID 38928583, 2024). "Researchers have investigated the clinical efficacy of mouse NGF on cognitive deficits by evaluating patient imaging performance." (PMID 39639374, 2024). "Aerobic exercise significantly increases the plasma levels of BDNF, nerve growth factor, motor activity, cognitive impairment, exploratory behavior, and spatial memory in people with AD." (PMID 37600508, 2023). "Cognitive deficits are associated with altered levels of several neurological factors, such as brain-derived neurotrophic factor (BDNF), nerve growth factor (NGF), and glial cell-derived neurotrophic factor (GDNF)." (PMID 36329874, 2022). "Neurotrophins, particularly BDNF and nerve growth factor (NGF), are another type of cytokines associated with cognitive impairment in psychiatric disorders." (PMID 36406755, 2022). "Taurine (dissolved in 1% and 2% tap water, respectively), ameliorates cognitive impairment and inhibits apoptosis of hippocampal neurons exposed to high Glucose in diabetic rats through the NGF-Akt/Bad pathway." (PMID 36187803, 2022). "Although several studies have confirmed that BDNF and NGF are expressed at lower levels in peripheral blood of patients with SCZ, MDD, and BD, their association with cognitive impairment remains controversial." (PMID 36406755, 2022). "Cognitive deficits that arise from an increased pro-NGF signaling are a consequence of the interaction between pro-NGF and p75NTR in the absence of its rival signaling partner mNGF." (PMID 34326765, 2021). "In support of this, pharmacologically induced chronic failure in NGF maturation has been shown to result in increased pro-NGF level, cholinergic degeneration, and cognitive impairment in rat models." (PMID 34326765, 2021).